INS (insulin)
Diseases named in the same sentence as INS in open-access papers (continued):
Sharing a sentence is not in itself a finding about the gene and the disease.
Insulin resistance (continued). "Insulin resistance in T2D increases the demand for insulin in insulin-target tissues." (PMID 36900596, 2023). "Thus, PIMT has been proposed to function as a negative regulator of insulin signaling, consequently promoting hepatic gluconeogenesis, prompting us to evaluate its expression in insulin resistance pathological models." (PMID 36866247, 2023). "The complex relationship between lipid infiltration of myocytes and insulin resistance is a topic of interest, and, in this section, we focus on the effects of lipids on different sites of the insulin action pathway and on organelles and summarize the results of research conducted in recent years." (PMID 36918975, 2023). "During MS development, the hypertrophic adipose tissue increases the release of free fatty acids (FFA), which may contribute to the development of peripheral insulin resistance and impaired insulin secretion by pancreatic beta cells." (PMID 36768281, 2023). "The normal insulin-mediated stimulation of LPL activities is interrupted by insulin resistance." (PMID 37007365, 2023). "Our data suggests that nondrug strategies such as spinach- derived thylakoid supplementation with HIFT can have protective effects on adipokines, glucose homeostasis parameters (insulin, glucose and insulin resistance); and body composition variables (weight, FM and FFM)." (PMID 37576981, 2023). "Then, due to the vital roles of insulin in activating nitric oxide, which is a potent vasodilator and antiatherogenic agent, any impairments in insulin signaling such as insulin resistance may lead to hypertension and subsequently CVDs." (PMID 36611151, 2023). "T2DM is mainly caused by insulin resistance and reduced insulin secretion; insulin resistance is when muscle, adipose cells, and liver cells do not respond well to insulin and cannot use glucose from the blood for energy." (PMID 37765290, 2023). "To reiterate, SARS-CoV-2 penetrates cells via the ACE2 pathway, and as ACE2 is extensively expressed in the liver and pancreas, it may have a role in insulin resistance and decreased insulin production." (PMID 36984473, 2023). "Finally, in two studies from Latin America (Mexico and Colombia), serum leptin, insulin, adiponectin levels, and a homeostatic model assessment for insulin resistance (HOMA-IR) predicted the variation in excessive GWG or were associated with higher pBMI." (PMID 36986260, 2023). "Besides, they also differ in the pattern of insulin secretion: IFG is more likely to have a decrease in early insulin secretion, which combined with hepatic insulin resistance, causes excessive hepatic glucose production and lead to fasting hyperglycemia." (PMID 37402708, 2023). "Therefore, NMES seems to have great potential to be used as an effective alternate strategy to improve glycemic control especially in physically inactive population with insulin resistance and T2D via insulin independent glucose uptake pathway." (PMID 37583429, 2023). "Therefore, Rg3 treatment promoted adiponectin secretion and alleviated insulin resistance in diabetic mice, as evidenced by reduced insulin, glucose, and free acid levels." (PMID 38069059, 2023). "In an oral glucose tolerance test, Gastaldelli A demonstrated that acute exenatide administration improves hepatic insulin resistance, hepatic glucose uptake and insulin’s antilipolytic effect, decreases endogenous glucose production, adipose insulin resistance and plasma free fatty acid levels." (PMID 37781697, 2023). "We have learned for decades that early intensive insulin therapy in patients with newly diagnosed T2D can bring favorable outcomes, while in T2D subjects with severe insulin resistance, high dose insulin treatment can be well‐tolerated and effective on improving glucose disposal." (PMID 36905134, 2023). "Furthermore, disposition index (early phase insulin secretion/homoeostasis model assessment of insulin resistance) was significantly lower in the PPM+ group compared to the M-group." (PMID 37333553, 2023).
Insulin resistance (continued). "Decreased insulin resistance in myostatin deficient rats was attributed to a significant activation of the AMPK signaling pathway and increased adiponectin, an insulin sensitizing adipocytokine, secretion which enhances the oxidation of fatty acids in skeletal muscles." (PMID 37576807, 2023). "Given that both are associated with increased insulin resistance and GDM (and consistent with higher GDM incidence in STOP), higher PRL and hPL may be essential to promote insulin secretion in response to cues brought on by alterations in 1C metabolism." (PMID 37049394, 2023). "Indeed, another relevant factor accounting for the discrepant findings is represented by the acknowledgement of insulin resistance or insulin sensitivity as explanatory covariates mediating the association between muscle strength and NAFLD." (PMID 36831008, 2023). "Accumulation of fat in the liver and pancreas may reduce insulin responsiveness, leading to insulin resistance and resulting in excessive glucose production in type 2 diabetes." (PMID 37823118, 2023). "Moreover, high TNF levels have been associated with alterations in insulin signaling, and treatment with neutralizing TNF antibodies has improved insulin resistance." (PMID 37374323, 2023). "In this study, we stimulated human first-trimester trophoblasts (HTR8) with insulin at a dose that is comparable to the concentration observed in patients with insulin resistance and observed that ID2 expression in these cells increased in a dose- and time-dependent fashion." (PMID 36768469, 2023). "Furthermore, Vrel, positively correlated with the baseline insulin concentration and insulin resistance, and negatively correlated with the insulin sensitivity and glucose disposition (p < 0.001)." (PMID 36771243, 2023). "One of the explanations is that insulin resistance is involved in skeletal muscle protein breakdown, and impaired insulin/IGF-I signaling could lead to a drop in phosphorylated Akt and muscle loss." (PMID 37265691, 2023). "Indeed, it has been reported that all the markers (insulin, adiponectin and homeostatic model assessment for insulin resistance) of insulin resistance (IR) increase during the period of GD12." (PMID 37298274, 2023). "Notably, chronic overdeposition of lipids results in insulin resistance (high-insulin level while low-insulin efficiency) and impairs the insulin-SREBP1 signaling-mediated lipogenesis in mammalians." (PMID 37520290, 2023). "Insulin resistance has been shown to contribute to endothelial dysfunction, manifested by impaired the transcapillary passage of insulin to target tissues, inadequate coronary dilation and/or abnormal vasoconstriction, and peripheral arterial microcirculation disturbances." (PMID 36678603, 2023). "Firstly, a recent meta-analysis revealed that diets with low levels of AGEs significantly decreased insulin resistance, fasting insulin, and total and LDL cholesterol, best reflected in subjects on prolonged low-AGE diets and with metabolic syndrome risk factors." (PMID 37446161, 2023). "It is possible that other TLR4-expressing cells in Tlr4LKO mice could influence insulin signaling molecules and contribute to alcohol-induced insulin resistance." (PMID 36979389, 2023). "Thus, a PBD has the potential to reverse β-cell dysfunction and peripheral insulin resistance in patients with type 2 diabetes, partly by improving glycemic control, reducing lipid accumulation in muscle and liver, and/or improving insulin sensitivity." (PMID 37513660, 2023). "Insulin resistance is related to the decrease of insulin capacity to uptake glucose and it may contribute to becoming a risk group for the development of metabolic syndrome in children." (PMID 36810017, 2023). "In addition, we observed higher fasting insulin levels in the male mice, further suggesting the mice were developing insulin resistance." (PMID 37198225, 2023).
Insulin resistance (continued). "Applying this method to estimate multiple measures of insulin resistance from identical clinical samples may provide insight into the relationship of different insulin resistance measures and their relative value to reflect risk of disease." (PMID 37558891, 2023). "In contrast, during conditions when insulin signaling is diminished, such as in fasting and insulin resistance states, AKT-mediated nuclear exclusion of FoxO decreases, which causes an overall increase in FoxO transcriptional activity to elevate hepatic glucose production and output." (PMID 37941908, 2023). "The reason might be that central obesity is more pronounced in reducing insulin sensitivity and increasing insulin resistance compared to other obesity types." (PMID 37711898, 2023). "Similarly, compared with other ethnic groups, South Asians tend to have high fat mass and low lean mass, which likely account for greater levels of insulin and insulin resistance in this group." (PMID 37237531, 2023). "Furthermore, we investigated the impacts of 4-CS in non-T2DM individuals (n = 3279) on T2DM-related indices, including blood levels of glucose, insulin, and hemoglobin A1c (HbA1c), as well as the homeostasis model assessment of insulin resistance (HOMA-IR)." (PMID 37626071, 2023). "Other studies have suggested that the beneficial effects of pioglitazone may be related to its insulin-sensitizing properties, which reduce insulin resistance in the adipose tissue, muscle, and liver." (PMID 37305429, 2023). "In female mice, androgen excess seems to promote chronic androgen receptor activation in pancreatic beta cells, leading initially to increased basal insulin secretion independently of insulin resistance and, eventually, to beta cell failure and hyperglycaemia through oxidative stress." (PMID 36484476, 2023). "Insulin resistance is ascribed to the direct, diabetogenic effects of growth hormone (GH), which prevail over the insulin-sensitizing effects of insulin-like growth factor 1 (IGF-1), probably due to higher glucometabolic potency of GH, IGF-1 resistance, or both." (PMID 36882643, 2023). "In multinomial adjusted models, those at the second tertile of dietary caffeine intake were more likely to have higher serum insulin (P = 0.04) and lower homeostatic model assessment of insulin resistance (HOMA-IR) values compared with first tertile (P = 0.03) in crude model." (PMID 37864190, 2023). "In addition to beta-cells, the accumulation of ceramides can occur in other insulin-sensitive tissues in obesity, such as adipose tissue and skeletal muscle, contributing to the development of insulin resistance and, therefore, to the pathogenesis of T2D." (PMID 36671568, 2023). "Insulin resistance increases at the onset of puberty, peaking at Tanner stage 3, but returns to baseline pre-pubertal levels by the end of puberty and girls are more insulin resistant than boys at all pubertal stages." (PMID 37441710, 2023). "Insulinemia (p = 0.0004), insulin sensitivity (p = 0.0001) and insulin resistance (p = 0.001), as well as the mean serum levels of adiponectin (p = 0.0003), chemerin (p = 0.0001) and their ratio (p = 0.005) were parameters with statistically significant higher mean values in this group." (PMID 37109222, 2023). "In intervention trials, whole egg intake has not been shown to have neutral or beneficial effects on fasting glucose levels or insulin resistance markers (e.g., plasma insulin, HOMA-IR) in young healthy adults, subjects with metabolic syndrome, or type 2 diabetes." (PMID 37686779, 2023). "Plasma insulin and insulin resistance (HOMA-IR) decreased from baseline in both groups." (PMID 37009872, 2023). "The anti-T2DM effect of H2 has been associated with improved insulin sensitivity, evidenced by increased insulin sensitivity index (ISI), decreased insulin resistance index (IRI) and homeostasis model assessment-insulin resistance (HOMA-IR) index, and improved glucose and insulin tolerance." (PMID 37111299, 2023).
Insulin resistance (continued). "Conversely, the disruption of IRS-2 adversely affects both peripheral insulin signaling and pancreatic β-cell function, resulting in a gradual decline in glucose homeostasis in IRS-2-deficient mice, primarily attributed to liver insulin resistance." (PMID 37850091, 2023). "Therefore, the reduction in insulin concentrations and the improvement in insulin resistance appear to be a direct consequence of this dietary regimen and not mediated by weight loss." (PMID 36904127, 2023). "SIRT4 shows a mitochondrial localization and is a lysine deacylase that controls insulin secretion: Sirt4 KO mice progressively develop glucose intolerance and insulin resistance, highlighting the importance of this mitochondrial enzyme in regulating leucine metabolism." (PMID 36901738, 2023). "However, there are significant heterogeneity between trials in the analysis results of insulin resistance (I2 = 86.7%, P < 0.05) and insulin (I2 = 91.3%, P < 0.05)." (PMID 37524765, 2023). "So, it is concluded that inhibiting the 11β-HSD1 may work in reducing insulin resistance and thus increasing insulin sensitivity by regulating the insulin signaling transduction system." (PMID 36782201, 2023). "Moreover, fasting insulin concentrations and homeostatic model assessment of insulin resistance were significantly higher in GDM patients carrying the T allele than in those with the CC genotype (P < 0.05)." (PMID 37264354, 2023). "A 75 g oral glucose tolerance test was performed to measure glucose and insulin values every 30 min over 2 h to calculate indices of insulin resistance (MATSUDA, HOMA-IR) and of absolute (AUCins/glu, HOMA-B) and insulin resistance-adjusted insulin secretion (ISSI-2)." (PMID 37891561, 2023). "Moreover, significant associations were identified between carboxylated osteocalcin with fasting insulin levels, insulin resistance (determined by HOMA-IR), and circulating testosterone levels." (PMID 37251667, 2023). "Thus, the liver-specific deletion of Bmal1 mimics the hepatic pathophysiology in T2D, which is characterized by elevated oxidative stress, decreased insulin signaling, ectopic lipid buildup, and hepatic insulin resistance." (PMID 36829576, 2023). "Weight, BMI, fasting glucose, fasting insulin and insulin resistance were improved after IF." (PMID 37297894, 2023). "Recently, it has been revealed that hepatocyte exosomes from early onset obese mice (4 weeks high-fat diet) express high levels of microRNA miR-3075, which improves insulin sensitivity, while hepatocyte-released exosomes from chronic obese mice (16–18 weeks high-fat diet) promote insulin resistance." (PMID 36757838, 2023). "Insulin resistance occurs when normal circulating concentrations of insulin fail to regulate glucose uptake and utilization in cells because of the relative insufficiency of insulin secretion and the decreased sensitivity of target organs to the hormone." (PMID 37103360, 2023). "The homeostasis model assessment (HOMA) index calculation (measurement of fasting insulin and glucose) showed that the dietary supplementation with both GT and RT was able to ameliorate the insulin resistance developed after the HFD diet up to almost normal values." (PMID 37727633, 2023). "The observed reduction in glucose AUC, PPI, and insulin AUC levels may explain the alleviation of insulin resistance." (PMID 37895834, 2023). "Insulin resistance impairs the blood-glucose-lowering effect of circulating or injected insulin." (PMID 37715850, 2023). "In consequence insulin signalling and insulin resistance are impaired." (PMID 37174886, 2023). "An increase in FFAs leads to hepatic insulin resistance by interacting with insulin signaling." (PMID 37895151, 2023). "Hesperidin could also affect insulin levels and insulin resistance by modulating inflammation since it has been shown that inflammatory markers, including leptin, IL-6, and TNF-α, play a role in the pathogenesis of DM and the development of insulin resistance." (PMID 37502716, 2023).
Insulin resistance (continued). "This type is characterized by insulin resistance, where the body's cells do not respond effectively to insulin, and relative insulin deficiency, where the pancreas does not produce enough insulin to compensate for the resistance." (PMID 38022307, 2023). "The simultaneous increase in glucose and insulin concentrations in obese animals may predict the development of insulin resistance." (PMID 36864815, 2023). "However, long-term use of GH counteracts the effects of insulin and induces insulin resistance and diabetes." (PMID 37886966, 2023). "Furthermore, in our cohort during pregnancy, insulin levels and insulin resistance, quantified by HOMA2-IR, positively correlated with raised ACBP concentrations in univariate analyses." (PMID 37872629, 2023). "Insulin resistance develops when insulin signaling is impaired; however, insulin resistance is compensated initially by increasing insulin secretion, but eventually, insulin release from pancreatic β-cells becomes insufficient for maintaining normal blood glucose concentration, which leads to T2D." (PMID 36982822, 2023). "Dietary restriction and exercise have been found to lower levels of insulin and insulin resistance." (PMID 37854186, 2023). "In research that was conducted among the Asian women with insulin resistance and baseline 25(OH)D levels below 20 ng/mL, it has been reported that vitamin D supplementation with dose of 4,000 IU led to a significant improvement in the insulin sensitivity." (PMID 36742396, 2023). "These detrimental changes might be contained by adopting a lifestyle that promotes low insulin/insulin resistance levels and enhances an adaptive response to cellular stress, as observed with dietary restriction or exercise." (PMID 37854186, 2023). "However, insulin concentrations were considerably elevated (0 min: 71 μU/mL; 60 min: 953 μU/mL), suggesting severe insulin resistance." (PMID 37042492, 2023). "We examined the associations of glucose metabolism indices, including fasting plasma glucose (FPG), 2-hour (2 h) oral glucose tolerance test (OGTT), hemoglobin A1c (HbA1c), fasting insulin level, homeostasis model assessment of insulin resistance (HOMA-IR), and HOMA-β and the development of CKD." (PMID 37564380, 2023). "Overall, we propose a model in which glucocorticoid-regulated insulin sensitivity is determined by the balance between glucocorticoid-modulated insulin resistance and insulin sensitizing genes, in which EHMT2 coactivation is specifically involved in the latter process." (PMID 37253782, 2023). "Notably, depletion of PIMT in pathological relevant insulin resistance animal models displayed significant improvement in hepatic insulin sensitivity positioning PIMT as a druggable target." (PMID 36866247, 2023). "In addition, for circFAT3 KD, genes related to insulin signaling and insulin resistance (PPARGC1A, SLC27A2, PPARGC1B, PRKCQ, GYS1, and IRS1) were the top hits." (PMID 36840844, 2023). "Insulin resistance may contribute to the expression of some myocardial cell hypertrophy genes, and high insulin levels, combined with insulin-like growth factor 1 receptor, may induce myocardial cell hypertrophy." (PMID 37691190, 2023). "The metabolites 1-carboxyethylphenylalanine and gamma-glutamylcitrulline are associated with insulin sensitive and insulin resistance regardless of activity." (PMID 37175541, 2023). "Insulin resistance (IR) is recognized as an impaired response of target tissues to insulin." (PMID 35986887, 2023). "Previous studies have confirmed that all patients, including women with GDM and T2DM, share a similar pathophysiology with impaired insulin secretion and increased insulin resistance, and that both diseases share common SNPs with similar degrees of size effects in similar risk alleles." (PMID 37836571, 2023).